EPN2 (epsin 2)
Description:
Plays a role in the formation of clathrin-coated invaginations and endocytosis.
Synonyms: KIAA1065; EHB21
Tractability: Antibody: its Gene Ontology location is reachable by antibodies, with medium confidence. PROTAC: UniProt records ubiquitination sites on it; ubiquitination databases record sites on it; its protein half-life has been measured.
Gene: Protein-coding gene on chromosome 17 (19,214,837 to 19,336,715, forward strand). Ensembl gene ENSG00000072134.
Subcellular location: Cytoplasm; Cytoplasmic vesicle, clathrin-coated vesicle
Subcellular location (Human Protein Atlas): Vesicles
Pathways (Reactome):
Vesicle-mediated transport: Cargo recognition for clathrin-mediated endocytosis; Clathrin-mediated endocytosis
Gene Ontology:
Molecular function: cadherin binding; protein binding; phospholipid binding
Biological process: negative regulation of sprouting angiogenesis; negative regulation of vascular endothelial growth factor receptor signaling pathway; positive regulation of Notch signaling pathway; endocytosis
Cellular component: cytoplasm; clathrin vesicle coat; cytosol; clathrin-coated vesicle
Genetic constraint (gnomAD): Loss-of-function variants: 28 observed, 47.75 expected, observed/expected ratio (o/e) 0.59, 90% interval 0.43 to 0.8. The upper end of that interval is the gene's LOEUF score, 0.8, which puts it in group 3 of 6, group 1 being the genes least tolerant of losing a copy. Missense variants: 630 observed, 745.96 expected, observed/expected ratio (o/e) 0.84, 90% interval 0.79 to 0.9. Synonymous variants: 322 observed, 325.66 expected, observed/expected ratio (o/e) 0.99, 90% interval 0.9 to 1.08.
Homologues: Orthologues: chimpanzee EPN2 (99% identical), macaque EPN2 (98% identical), dog EPN2 (92% identical), guinea pig EPN2 (92% identical), rat Epn2 (89% identical), mouse Epn2 (89% identical), pig EPN2 (78% identical), rabbit EPN2 (65% identical), tropical clawed frog epn2 (64% identical), zebrafish epn2 (58% identical), Drosophila melanogaster lqf (40% identical), Caenorhabditis elegans epn-1 (32% identical). Paralogues in human: EPN3 (44% identical), EPN1 (43% identical), ENTHD1 (24% identical), CLINT1 (23% identical), MYCBPAP (13% identical).
Diseases named in the same sentence as EPN2 in open-access papers:
EPN2 is named in the same sentence as 8 diseases in open-access papers, as found by Europe PMC text mining. Sharing a sentence is not in itself a finding about the gene and the disease. The quoted sentences say what the papers report.
atherosclerosis (2 papers, 2020 to 2022). A disease characterized by the build-up of fatty material and calcium deposition in the arterial wall resulting in partial or complete occlusion of the arterial lumen. "To understand the in vivo role of epsins in facilitating atherosclerosis through endothelial cell dysfunction, we employed the ApoE−/− atherosclerotic mice with an endothelial cell-specific deletion of epsin 1 on a global epsin 2 knock-out background (EC-iDKO/ApoE−/−) 18,19,25." (PMID 32770009, 2020).
schizophrenia (2 papers, 2022 to 2023). A major psychotic disorder characterized by abnormalities in the perception or expression of reality. "Interestingly, other variants were found in hmsLRI-E connected to genes that had not been previously associated with schizophrenia (KIZ, CDKAP2, EPN2, MAPK7, B9D1)." (PMID 35887306, 2022).
Alzheimer disease (1 paper, 2022). A progressive, neurodegenerative disease characterized by loss of function and death of nerve cells in several areas of the brain leading to loss of cognitive function such as memory and language. "Interestingly, three of these genes (EPN2, SNX15, and DGCR8) have previously been associated with hippocampal functioning and processes linked to the development of Alzheimer’s disease (AD)." (PMID 35933470, 2022).
tumor (2 papers, 2017 to 2023). "EPN2 in vitro samples overlapped with the primary tumor tissue on the PC1 component and only varied significantly on the PC2 component." (PMID 37508868, 2023). "Interestingly, the predominance of 3D co-cultures in EPN2 in vitro samples could have contributed to the separation of EPN2 in vitro models from the primary tumor tissue regarding their transcriptomic profiles." (PMID 37508868, 2023).
cancer (1 paper, 2023). A tumor composed of atypical neoplastic, often pleomorphic cells that invade other tissues. "Compared with paracancerous tissues, AKAP7, EFEMP1, EPN2 and LAMA2 were lowly expressed in cancer tissues, while RPS6KA1, SLC1A6, TRABD and ZNRD1 were highly expressed in cancer tissues." (PMID 37123010, 2023).
infection (1 paper, 2022). The state of being infected such as from the introduction of a foreign agent such as serum, vaccine, antigenic substance or organism. "Heterogeneous nuclear ribonucleoprotein D (HNRNPD), epsin 2 (EPN2), and tripeptidyl peptidase 1 (TPP1), among others, showed reduced protein levels when cotransfected with CTSW compared to their levels in the green fluorescent protein (GFP) control, regardless of infection." (PMID 35867415, 2022).
EPN2 also shares sentences with these, for which no sentence is quoted: bladder cancer (1 paper); glioblastoma (1).